FSTL1 (follistatin like 1)
Diseases named in the same sentence as FSTL1 in open-access papers (continued):
Sharing a sentence is not in itself a finding about the gene and the disease.
FSTL1 also shares sentences with these, for which no sentence is quoted: esophageal squamous cell carcinoma (5 papers); ulcerative colitis (4); non-small cell lung carcinoma (3); colon cancer (2); dermatomyositis (2); head and neck squamous cell carcinoma (2); idiopathic pulmonary fibrosis (2); IgA nephropathy (2); kidney cancer (2); lung squamous cell carcinoma (2); polymyositis (2); reactive arthritis (2); systemic sclerosis (2); acute myocardial infarction (1); bacterial infection (1); bladder tumors (1); brain tumors (1); bronchopulmonary dysplasia (1); cerebellar ataxia (1); chronic hepatitis B (1); congenital heart disease (1); coronary artery atherosclerosis (1); COVID-19 (1); diastolic heart failure (1); dilated cardiomyopathy (1); dissection (1); epilepsy (1); esophageal cancer (1); gout (1); head and neck cancer (1).
A further 26 diseases each share a sentence with FSTL1 in 1 paper.